CD40 (CD40 molecule)
Diseases named in the same sentence as CD40 in open-access papers (continued):
Sharing a sentence is not in itself a finding about the gene and the disease.
metabolic disease (4 papers, 2017 to 2025). A congenital disorder (due to inherited enzyme abnormality) or acquired (due to failure of a metabolically important organ) disorder resulting from an abnormal metabolic process. "CD40-expressing adipocytes are essential in modulating immune cell responses, especially in cardiovascular and metabolic disease progression." (PMID 39899926, 2025). "We proposed signal 4 (MADS recognition) for BC activation because the CD40:CD40L immune checkpoint is involved in BC activation and sCD40L is induced in metabolic disease including CKD, HHcy, hypertension, hyperglycemia, and dyslipidemia." (PMID 28738836, 2017). "However, studies show that both CD40 knockout mice and CD80/CD86 double knockout mice under HFD feeding exhibit exacerbated adipose tissue inflammation and metabolic disorders." (PMID 33329579, 2020).
gastrointestinal tumors (3 papers, 2010 to 2025). "Studies have also shown that activated CD40 can improve the immunomodulatory ability of dendritic cells toward gastrointestinal tumors." (PMID 40551711, 2025). "Of the top 10 genes that were hypermethylated in CIMP-H compared to CIMP-L tumors, 5 have previously been implicated in the pathogenesis of gastrointestinal tumors (NTRK3, HS3ST2, TWIST1, CD40 and EYA4)." (PMID 20492682, 2010).
inflammation (3 papers, 2015 to 2019). Aberrant reaction of the microcirculation characterized by movement of fluid and leukocytes from the blood into extravascular tissues. "Anti-CD40 siRNA therapy significantly increased the density of peritubular capillaries and decreased renal inflammation in the ATH model." (PMID 31889910, 2019). "Conversely, administration of agonist anti-CD40 mAb to LNG-treated mice at dpi 1 produced Chlamydia burden and pulmonary inflammation at 12 dpi that closely resembled that seen in placebo-pelleted controls." (PMID 27892938, 2016).
genetic disease (2 papers, 2020 to 2021). "Within the genetic disorders, so far, six genes have been implicated, coding for molecules involved in CD40 and CD40 ligand signaling (CD40 and CD40L), or in cytosine and cytidine deaminase process (AID)." (PMID 32192142, 2020).
retinopathies (2 papers, 2015 to 2019). "The CD40 pathway is activated in these retinopathies and CD40 has emerged as a central mediator of inflammatory responses and pathology in these disorders." (PMID 31921199, 2019). "CD40 is central for the development of retinal inflammation and retinopathy induced by I/R." (PMID 31921199, 2019).
vasculopathy (1 paper, 2022). "CD40+ infiltrates colocalize with CD154 expression in glomeruli and tubules suggesting a role in mediating pro-inflammatory signaling in the kidney and as discussed a role in the development of vasculopathy observed during chronic rejection." (PMID 35464470, 2022).
CD40 also shares sentences with these, for which no sentence is quoted: multiple myeloma (10 papers); vasculitis (5); hematological cancer (4); renal carcinoma (4); Cognitive impairment (3); heart disease (3); Hyperinsulinemia (3); Hypoglycemia (3); osteoarthritis (3); Parkinson disease (3); pneumonia (3); psoriasis vulgaris (3); rectal cancer (3); Wiskott-Aldrich syndrome (3); acute myocardial infarction (2); Aortic dissection (2); autoimmune lymphoproliferative syndrome (2); biliary tract infections (2); bipolar disorder (2); celiac disease (2); cerebral malaria (2); deep vein thrombosis (2); fibrosis (2); head and neck tumor (2); HIV associated dementia (2); liposarcoma (2); lobular carcinomas (2); Lymphadenopathy (2); MALT lymphoma (2); Pitt-Hopkins syndrome (2).
A further 127 diseases each share a sentence with CD40 in 2 papers or fewer.